IL6 (interleukin 6)
Diseases named in the same sentence as IL6 in open-access papers (continued):
Sharing a sentence is not in itself a finding about the gene and the disease.
depression (continued). "It is known that people with major depressive disorder and early life stress have elevated IL-6 levels in response to TSST." (PMID 36231182, 2022). "CES-D The Center for Epidemiologic Studies Depression Scale; IADLs Instrumental Activities of Daily Living; IL-6 Interleukin-6; hsCRP High sensitivity C-reactive protein." (PMID 35279110, 2022). "It has become common to treat depression according to the inflammatory mechanism and pro-inflammatory cytokines (such as IL-1 β, IL-6, and TNF-α)." (PMID 35682841, 2022). "In particular, IDO has been reported to catalyze the production of kynurenine from tryptophan in the brain, causing neuroinflammation, depression, and cognitive dysfunction by activating pre-inflammatory cytokines (IFN-γ, TNF-α, IL-1, and IL-6)." (PMID 35719088, 2022). "Depression-like symptoms can be alleviated by increasing the expression of Nrf2/HO-1 and decreasing the expression of IL-1β, IL-6, and TNF-α in the microglial cells." (PMID 35634375, 2022). "For example, the difference in the amount of IL-6 in the group with depression was ninety-fold greater than in the controls (978.1 pg/mL versus 11.1 pg/mL)." (PMID 35409300, 2022). "In the chronic inflammatory state associated with stress, Interleukin (IL)-1beta, Tumor Necrosis Factor (TNF)-alpha and IL-6 have been reported to be the most represented cytokines; Serum C-Reactive Protein, IL-1 and IL-6 were the most prevalent in depression." (PMID 35323251, 2022). "Patients with depression often show signs of inflammation, which was illustrated by the increased concentrations of cytokines such as IL-1, IL-6, and TNF-α in the peripheral blood and cerebrospinal fluid." (PMID 35411516, 2022). "IL-6, rKT, QUIN, and KYN measured in the 2nd trimester have strong evidence (>95% chance) of being positively associated with both depression severity (EPDS) and risk of significant depressive symptoms (EPDS ≥ 13) in the 3rd trimester." (PMID 35078975, 2022). "Maladaptive inflammatory responses to various stressors leading to elevation in pro-inflammatory cytokines such as interleukin 1β, interleukin 6, and tumor necrosis factor α is another proposed mechanism of depression." (PMID 35606688, 2022). "For example, increased levels of C-reactive protein (CRP), interleukine-6 (IL-6) and tumor necrosis factor-α have been repeatedly observed in patients with depression." (PMID 36447174, 2022). "The research results of elderly patients with depression show higher levels of IL-6 than in healthy elderly people." (PMID 36364213, 2022). "Elevated levels of pro-inflammatory cytokines including Interleukin (IL)-1, IL-6, IL-8, and IL-12 were reported in individuals suffering from depression." (PMID 35546876, 2022). "A meta-analysis concluded that IL-1β was significantly elevated in patients with depression and Alzheimer’s disease (AD), while IL-6 was elevated only in patients with depression." (PMID 36614020, 2022). "It is noteworthy that IL-1β, IL-6, and IL-10 are the most frequently reported cytokines in depression and affective disorders." (PMID 36387880, 2022). "This has been supported by meta-analyses showing high levels of the same proinflammatory cytokines like RA (IL6, IL1β, and TNFα) in the peripheral blood of patients with depression compared with controls." (PMID 36422176, 2022). "Studies have shown that Rg1 reduced the levels of IL-1β, TNF-α, caspase-1, IL-2, IL-6 and IL-18 via the suppression of Connexin43 (Cx43) ubiquitination in depression." (PMID 36010610, 2022). "Fluoxetine, the main medication for the treatment of depression reduces the levels of IL-6 and TNF-α in patients." (PMID 36431060, 2022). "Patients with major depression exhibit significant inflammatory responses, including the increased expression of pro-inflammatory cytokines such as interleukin 6 (IL-6), interleukin 18 (IL-18) and tumor necrosis factor α (TNF-α)." (PMID 35334870, 2022).
depression (continued). "TNF-α and IL-6 are two common inflammatory cytokines involved in the neuroinflammatory response in depression." (PMID 36431060, 2022). "Serum TNF‐α, IL‐1β, IL‐6, and IL‐17 are related to increased anxiety and depression risks to some extent in NSCLC survivors." (PMID 34697903, 2022). "According to our previous review, IL-6, IFN-α, and TNF-α and CRP were associated with depression and anxiety." (PMID 35053845, 2022). "Findings also suggest the possibility that elevated IL-6 levels are more relevant for the pathogenesis of psychosomatic syndromes than for depression in patients with HF." (PMID 35271674, 2022). "For example, meta-analyses of psychoneuroimmunology showed tumor necrosis factor (TNF)-α, interleukin (IL)-1, and IL-6 levels were significantly increased in patients with depression symptoms." (PMID 35163263, 2022). "Of note, the correlations of TNF‐α and IL‐1β with depression were more obvious compared with IL‐6 and IL‐17." (PMID 34697903, 2022). "Previous studies in depression and suicidality have found increased levels of cytokines, in particular IL-6, and kynurenine metabolites, in blood and CSF of patients with depression and suicidality." (PMID 35078975, 2022). "In the clinical aspects, preceding evidence suggests the association of inflammatory cytokines (such as TNF‐α, IL‐8, and IL‐6) with anxiety and depression in cancers, such as colorectal cancer, breast cancer, and pancreatic cancer." (PMID 34697903, 2022). "Pro-inflammatory cytokines such like TNF-α and IL-6 have been shown to be increased in patients with depression, and human volunteers were indeed induced anxiety and depression by the treatment with pro-inflammatory cytokine IFN-α." (PMID 35558075, 2022). "For instance, an RCT revealed that psychotherapy simultaneously decreased depression scores and IL-6 and TNFα values, which were correlated with the social role component of one score." (PMID 36291336, 2022). "Data consistently demonstrates that a subset of patients with depression show elevated levels of inflammatory biomarkers including Interleukin-6 (IL-6), Interleukin-1Beta (IL-1β), Tumour Necrosis Factor-alpha (TNF- α) and CRP." (PMID 35146459, 2022). "Clinical and animal research revealed that increased IL-6 and decreased IL-10 would result in depression." (PMID 35757220, 2022). "Although depression is characterized by high IL-6 levels, the relationship between natural killer cells and IL-6 has not been proven in humans." (PMID 36386785, 2022). "Increased levels of IL-6 and CRP are not only associated with major depression, but also with RA, and in the latter illness, IL-6 is associated with increased CDAI, DAS28, and bone erosions." (PMID 35330475, 2022). "The COX-2 inhibitor celecoxib was shown to improve depression symptoms in patients with the major depressive disorder, potentially decreasing IL-6 levels." (PMID 35927237, 2022). "We found that IL-6 correlated positively with the key KP metabolite involved in depression, KA, although the effect size was small (R = 0.20, p = 0.0079)." (PMID 36299996, 2022). "At present, many studies have confirmed that the levels of inflammatory factors such as IL-1β and IL-6 in the serum of patients with depression are dramatically increased." (PMID 35148670, 2022). "Patients with depression had significantly lower cerebrospinal fluid levels of IL-6 as compared to controls (p = 0.014) in the univariate analysis." (PMID 36172507, 2022). "A recent cross-sectional study in post partum women with severe and suicidal depression indicated the presence of higher levels of IL-6 and IL-8 and reduced concentrations of IL-2, 5-HT, and quinolinic acid in plasma due to dysregulation of kynurenine pathway." (PMID 36611848, 2022). "Compared with the non-depression group, patients with depressive symptoms had higher levels of inflammatory cytokines, including IL-1, IL-6, TNF-α, and CRP." (PMID 35757220, 2022).
depression (continued). "The most common cytokines associated with poor psychological outcomes involving PTSD and/or depression in the chronic mTBI population were IL-6, TNFα, IL-10, and CRP." (PMID 35053845, 2022). "Increased serum levels of inflammatory markers IL-1 and IL-6 are observed among patients suffering from depression when compared to healthy controls." (PMID 35407580, 2022). "The main result indicates that peripheral levels of IL-6 were significantly lower after CBT intervention in individuals with depression, with a small effect (SMD = 0.38, 95% CI: 0.07, 0.69, p = 0.02)." (PMID 35633813, 2022). "Various studies demonstrate that, e.g., schizophrenia, depression, suicidal ideation and post-traumatic stress disorder are characterized with increased levels of inflammatory markers, particularly IL-1β, IL-2R, IL-6, IL-17A, TNF-α and CRP." (PMID 35682824, 2022). "In reaction to stressful stimuli, the synthesis of IL-6 increases, and findings suggest that in depression, higher IL-6 levels correlate with a more severe course of the disease." (PMID 36614020, 2022). "We aimed to evaluate serum tumor necrosis factor‐α (TNF‐α), interleukin‐1 beta (IL‐1β), interleukin‐6 (IL‐6), interleukin‐17 (IL‐17) levels, and their correlations with anxiety/depression in NSCLC survivors." (PMID 34697903, 2022). "Th17 cell number, a subset of proinflammatory T-helper cells, also increases in depression, most likely due to higher serum IL-6 levels." (PMID 36613927, 2022). "Our results are also in agreement with several studies suggesting that IL-6 is involved in the pathophysiology of psychosomatic disorders and fibromyalgia independently of comorbid medical conditions including depression." (PMID 35271674, 2022). "The data suggest that NFATc4 in the mPFC plays a role in depression-like phenotype and increases in blood levels of IL-6 of LPS-treated mice." (PMID 35064103, 2022). "A rat model of EAP complicated with depression was established and confirmed by increases in IL-1β, IL-6, and TNF-α as well as the occurrence of depressive‐like behaviors." (PMID 36250064, 2022). "An association between IL-2, IL-6, IL-8, TNF-α and VEGF levels and the severity of depression have been reported." (PMID 36045388, 2022). "Cytokines are also markers of immune cell activity and a meta-analysis of CSF samples comparing patients with depression to controls found increased levels of the pro-inflammatory cytokines IL-6 and IL-8 in CSF." (PMID 35022028, 2022). "To validate that our model was successful and verify the relationship between central and peripheral cytokines and depression, we measured the mRNA expression and protein level of pro-inflammatory cytokines, including IL-6, IL-1β and TNF-α." (PMID 36357867, 2022). "In the prefrontal cortex of a rat model of depression, interleukin (IL)-1β, IL-6, tumor necrosis factor-α (TNF-α), microglial activation, and NF-κB signaling are upregulated." (PMID 35496318, 2022). "CIA mice displayed depression-like behaviors, increased blood levels of pro-inflammatory cytokine interleukin-6 (IL-6), decreased expression of synaptic proteins in the prefrontal cortex (PFC), and abnormal composition of gut microbiota." (PMID 35650202, 2022). "Researchers have demonstrated that the levels of plasma interleukin 6 (IL-6) in patients with BC and depression are higher and are also regulated by sEH." (PMID 36364213, 2022). "In the last few years, numerous studies further revealed that besides IFN-α, the proinflammatory cytokines IL-6 and TNF-α and increased blood levels of the C-reactive protein (CRP), in particular, are associated with depressive disorders." (PMID 36358455, 2022). "Cortisol levels are related to both severity of depression and anhedonia, whereas the levels of IL-6 and CRP are merely related to anhedonia, which suggests that patients with anhedonic MDD have unique neuroendocrine-immune characteristics." (PMID 36090246, 2022).
depression (continued). "The authors of the third study found that patients with sole depressive disorder had higher CSF levels of IL-6 compared to patients with Parkinson's disease and comorbid depressive disorder." (PMID 36172507, 2022). "Herein, in this study, we aimed to determine how the serum IL-6 and IL-17 changes in patients with first-episode depressive disorder (FDD) before and after treatment and finally determine the association between autoimmunity and FDD." (PMID 35615531, 2022). "Reports consistently suggest that increased IL-6, TNF-α, and CRP levels are risk factors for mood and depressive disorders." (PMID 35558424, 2022). "The most often examined cytokine, interleukin-6 (IL-6), has repeatedly been found to be increased in depressive disorders." (PMID 36475229, 2022). "In the group with poststroke depressive disorder, salivary α-amylase was constantly elevated, while serum IL-6 was minimal during the acute period." (PMID 36547090, 2022). "In general, antidepressant medications tend to reduce the levels of pro-inflammatory factors, such as TNF-α, IL-1β, and IL-6, found in many patients with depressive disorders." (PMID 35252227, 2022). "High levels of IL-6 have been noted in the blood and/or CSF of patients suffering from depressive disorders, schizophrenia, PTSD, and sleep disorders." (PMID 34648616, 2022). "Patients with depressive disorders had significantly lower CSF levels of IL-6 as compared to controls (p = 0.014) in the univariate analysis, also after correction for multiple testing." (PMID 36172507, 2022). "Induction of depression-like behavior via learned helplessness paradigm furthermore resulted in an increased IL-6 expression within the hippocampus." (PMID 33683478, 2021). "Pro-inflammatory properties of IL-6 and its elevated levels in patients with depression were reported in most studies." (PMID 33920992, 2021). "In another study that correlated adipose inflammation and depression, symptoms of depression were shown to promote weight accumulation, which in turn activated an inflammatory response of IL-6 and Leptin54." (PMID 33741982, 2021). "Alterations in IL-6 levels, both within the periphery and the brain, most probably contribute to depression symptomatology in numerous ways." (PMID 33593388, 2021). "Interferons supposedly induce depression mainly by decreased serotoninergic transmission and hyperactivity of the hypothalamic–pituitary–adrenal axis (with high serum cortisol and IL-6 levels)." (PMID 34945228, 2021). "IL-6 is the most commonly studied cytokine, and has been consistently identified as being elevated in depression." (PMID 34211407, 2021). "A considerable number of studies have identified that interleukin-6 (IL-6) contributes substantially to major depressive disorder." (PMID 34299040, 2021). "A meta-analysis showed that patients with major depressive disorder had higher levels of plasma IL-6, TNF-α, and soluble interleukin-2 receptors (sIL-2R)." (PMID 34295268, 2021). "In a study involving a group of oncological patients with depression symptoms, it was shown that psychological intervention in the form of group therapy decreased both the symptoms of depression and the level of IL-6." (PMID 34945157, 2021). "Our findings lend support to RCTs testing immunotherapies targeting the IL-6/IL-6R pathway for patients with depression." (PMID 34505025, 2021). "For example, higher plasma IL-6 levels were found in patients with chronic back pain and comorbid depression and in patients with burning mouth syndrome and depressive symptoms than in healthy controls." (PMID 34526064, 2021). "Early life stress causes an inflammatory immune phenotype characterized by increased pro-inflammatory cytokines (IL-1β, IL-6, TNF-α) which are also associated with depression." (PMID 33807290, 2021).
depression (continued). "The FN transplantation into mice with RS-induced anxiety and depression markedly inhibited the RS-induced anxity- and depression-like behaviors, NF-κB activation in the hippocampus, and IL-6 and corticosterone levels in the blood." (PMID 34391441, 2021). "In particular, an increase in proinflammatory cytokines like IL-6 and TNF-α and a decrease in the neurotrophin BDNF are often associated with anxiety and depression in patients as well as experimental models." (PMID 34638592, 2021). "Subsequent research showed that administration of low-dose endotoxin (e.g., lipopolysaccharide (LPS)) increases systemic markers of inflammation including tumor necrosis factor alpha (TNFα) and interleukin 6 (IL-6) and symptoms of depression." (PMID 33967944, 2021). "We have also previously reported that IL-6R variants associated with higher serum IL-6 levels (but decreased IL-6R activity) and CRP variants associated with higher CRP levels are both associated with increased risk of depression in the UK Biobank." (PMID 34135474, 2021). "This is because a protective effect of CRP on schizophrenia risk fully attenuated in MVMR analysis after accounting for the effects of IL-6 and sIL-2Rα, and we didn’t find evidence for an association of CRP with depression, in line with other MR evidence." (PMID 34280516, 2021). "It has even been proposed that IL-6 elevation should be considered a biological marker of depression." (PMID 33920992, 2021). "A recent metanalysis characterized an inflammation profile in depression with elevated IL-6, tumor necrosis factor (TNF)-alpha, other cytokines, and chemokines." (PMID 33801190, 2021). "For men, higher interleukin-6 levels and higher hs-CRP levels were associated with depression and social isolation, higher leptin levels predicted depression and social isolation." (PMID 33614574, 2021). "Furthermore, having tested outcome-specific vs common effects, we report some of the first evidence for similar associations for IL-6 with psychotic and depressive outcomes, suggesting that childhood IL-6 could be a shared risk factor for adult psychosis and depression." (PMID 33684738, 2021). "Using genetic variants in the IL6R and CRP gene loci, we have found that higher genetically predicted IL-6 activity was associated with increased risk of depression, but higher genetically predicted CRP levels were associated with decreased risk of depression." (PMID 34505025, 2021). "Clinical studies have reported that the severity of depression in patients with PSD is positively correlated with the levels of IL-6, TNF-α, and IL-1β." (PMID 34725556, 2021). "After taking into account CRP and sIL-2Rα, increased IL-6 levels were associated with increased risk for both schizophrenia (IVW OR=1.26; 95% C.I., 1.05-1.52) and major depression (IVW OR=1.08; 95% C.I., 1.03-1.12)." (PMID 34280516, 2021). "Metaanalyses have shown higher concentrations of cytokines such as IL1ß, TNFα, and IL6 in the peripheral blood of patients with depression compared to healthy controls." (PMID 34773692, 2021). "For example, sleep deprivation has been related to higher levels of IL-6, and the dysregulation of sleep is common in patients with depression." (PMID 34358084, 2021). "Another reason for increased TNF-α and IL-6 in the serum in this study was the occurrence of CUMS-induced depression as they have been reported to be elevated in patients with depression and mice showing behavioral despair." (PMID 34040528, 2021). "The application of 60 V PRF immediately after SNI attenuated pain behaviors and consequent depression-like behavior, and downregulated proinflammatory IL-6 cytokine levels and modulated the descending serotoninergic pathway in rats." (PMID 34680606, 2021). "As IL-6 acts on so many diverse tissues throughout the organism, dysregulation of this cytokine can precipitate a multitude of events relevant to depression." (PMID 34934041, 2021).